ERBB2 (erb-b2 receptor tyrosine kinase 2)
Diseases named in the same sentence as ERBB2 in open-access papers (continued):
Sharing a sentence is not in itself a finding about the gene and the disease.
tumor (continued). "For example, trastuzumab and pertuzumab are monoclonal antibodies that target the extracellular domain and are used for the treatment of ErbB2/HER2-positive tumours." (PMID 38887279, 2024). "In the context of targeted delivery studies, the Human Epidermal Growth Factor Receptor 2 (HER2/ERBB2) exposed on selected tumor cells represents a widely recognized model receptor." (PMID 39402557, 2024). "We further constructed a xenograft tumor model in mice using control and ERBB2 overexpression T24 cells." (PMID 39840049, 2024). "TOB1 is a tumor-suppressing protein that functions as a negative regulator of the receptor tyrosine-kinase ERBB2." (PMID 38512977, 2024). "A good example are drugs targeting tumours over-expressing the ERBB2/HER2 protein (henceforth called HER2)." (PMID 39335175, 2024). "Oncogenes (e.g., NOTCH1 and ERBB2) tended to increase in centrality in tumor modules while tumor suppressors (e.g., BAP1, AKT1, and EP300) decreased in centrality." (PMID 38685127, 2024). "Collectively, these observations argue that, while ketosis can exacerbate ErbB2+ tumor growth, combining it with FAO blockade via Cpt1a targeting is an effective therapeutic strategy." (PMID 39097623, 2024). "Regarding GBC, KIF11 transfection was determined to be capable of facilitating tumor growth via an effect on the ERBB2/PI3K/Akt signaling pathway." (PMID 38433242, 2024). "Estrogen also plays a role in the PI3K/AKT pathway, which mediates the ERBB2/ERBB3 oncogenic signalling pathway that promotes tumour development and progression." (PMID 38974022, 2024). "Given that Etomoxir inhibits all Cpt1 isoforms, these results indicate that Cpt1a is the primary isoform driving FAO in ErbB2+ tumor cells." (PMID 39097623, 2024). "Fibroblast production of CXCL12/SDF-1 was shown to promote tumor cell proliferation by the activation of the CXCR4/ErbB2 axis." (PMID 38360674, 2024). "HER2 heterogeneity was defined as HER2-negative regions detected by fluorescence in situ hybridization (FISH) in 10% of cases, or ERBB2 gene amplification detected in more than 5% but fewer than 50% of tumor cells." (PMID 39655080, 2024). "Genetic testing showed that Erb-B2 receptor tyrosine kinase 2 (ERBB2) p.5310F mutation rate was 17.7%, Tumor mutational burden-high (TMB-H) was 2.87, Microsatellite instability-high (MSI-H) was 10.68%, TPS was <1%, and CPS was <1." (PMID 39045556, 2024). "We have shown that the presence of ecDNA can be observed early in dysplastic BE13 and in our study with P43 with the same ERBB2 ecDNA in both the Barrett’s and tumor biopsy." (PMID 38744814, 2024). "Currently, Her-2, also known as ERBB2, and combined positive score/tumour proportion score have been identified as therapy targets in advanced-stage disease via Trastuzumab and Immunotherapy including Pembrolizumab, Nivolumab and Camrelizumab, respectively." (PMID 39021541, 2024). "Tumours were grouped based on molecular subtype, including ERBB2 + (ER−, PR−, HER2+), triple negative (ER−, PR−, HER2−), Luminal-A (ER+ and/or PR+, HER2−), and Luminal-B (ER+ and/or PR+, HER2+)." (PMID 38114526, 2023). "The in vivo experiments using the CAM model represent the pre-clinical proof of concept for using the specific PPRHs against ERBB2 to inhibit tumor growth." (PMID 37108234, 2023). "We also did not observe higher expression of ERBB2 in ER − HER2 + compared to ER + HER2 + cell lines and tumours, which speaks against HER2 amplification level and/or expression driving the observed difference in EDI3 expression between these two subtypes." (PMID 36670508, 2023).
tumor (continued). "Patients with tumor mutations in the erythroblastic leukemia viral oncogene homolog (ErbB) family, including EGFR and ErbB2, had a significantly shorter disease-free survival than those with wild-type EGFR or ErbB2." (PMID 36149029, 2023). "One arm of the bispecific antibody is responsible for the ErbB2 targeting of the complex, while the second arm forms the antibody–interferon neutralizing complex, which dissociates at the tumor site." (PMID 36839658, 2023). "A study investigating the prevalence of ERBB2 amplification in different tumours identified ERBB2 amplification in 2 of 7 (28%) UrC samples." (PMID 36670542, 2023). "While less pronounced, a similar trend was observed for other target tumor cells with high or more moderate ErbB2 expression." (PMID 36688995, 2023). "Mutation of ERBB2/ERBB3 results in an abnormal activation of ERBB signaling pathway and promotes tumor proliferation and metastasis, which can be inhibited by regorafenib." (PMID 37681031, 2023). "In vivo ErbB2-targeted IFN-β demonstrates considerable tumor growth suppression in humanized mouse gastric cancer xenograft models in a direct manner." (PMID 36839658, 2023). "ERBB2 was replicated through elevated gene transcription in various of cancer cells, and tumor growth depended on ERBB2 amplification heavily." (PMID 37056778, 2023). "This study showed that PUVA also minimizes the p85ErbB2 phosphorylation in ErbB2+ breast cancers, which leads to the apoptosis of tumor cells." (PMID 36672732, 2023). "We first evaluated ERBB2 gene expression by reverse transcription polymerase chain reaction (RT–PCR) in 24 tumor samples obtained at baseline with ≥30% of tumor cells." (PMID 37488289, 2023). "The expression level of the ErbB2 protein in tumor tissues was found to be obviously higher than that in normal tissues in BSG patients." (PMID 36805678, 2023). "In LUAD, ErbB2 has been identified as one of the driver genes, and its inhibition can attenuate tumor progression and cell invasion." (PMID 37990309, 2023). "Human epidermal growth factor receptor 2 (HER2/ERBB2) is an oncogenic driver of tumour cell proliferation and metastasis." (PMID 37078460, 2023). "This approach destabilized and degraded ERBB2 and its kinases across many cancer ERBB2 models and achieved primary tumor control in vivo." (PMID 37359373, 2023). "More so, for these trastuzumab-resistant ERBB2-driven cancer patients, regional and distant organ metastasis of the tumor is a significant obstacle to good clinical outcomes." (PMID 37359373, 2023). "The univariate analysis of survival demonstrated that HBV infection, Child–Pugh class, maximal tumor diameter, AFP, BCLC stage, treatment modality, ERBB2, and NRG4 were significant risk factors." (PMID 37174100, 2023). "We also identified important biologic factors to explain the racial and ethnic disparities in pCR rates as tumor grade for HR+/ERBB2− subtype and ERBB2/CEP17 ratio for HR−/ERBB2+ subtype." (PMID 36995711, 2023). "The leading biomarkers that led to treatment recommendations were tumor mutational burden‐high (TMB‐H) (n = 32), ERBB2 amplification (n = 24), BRAF V600E (n = 16), and BRCA1/2 alterations (n = 32)." (PMID 36251535, 2023). "This context was mimicked by examining release from cytostatic doses of the dual ErbB inhibitor, lapatinib, in TM15 clone 6 (TM15c6) cells derived from an Erbb2-amplified tumor of a PMMTV-Cre;Erbb2+/V660E knockin mouse." (PMID 37055441, 2023). "Some studies have demonstrated that YY1 overexpression in breast cancer cell lines leads to tumor promotion through the ERBB2 and Akt/Cyclin D1 pathways." (PMID 37444605, 2023). "ErbBs are variably expressed in different tumours; ErbB1 and ErbB2 subtypes are the most over expressed in tumours, whereas the ErbB3 and ErbB4 are the least expressed." (PMID 38203605, 2023).
tumor (continued). "HER2 (ERBB2) gene amplification leads to Her-2 protein overexpression, which inhibits tumor apoptosis and promotes tumor cell invasion, vascular invasion, and lymphatic metastasis." (PMID 38074671, 2023). "MET, ERBB2, VEGFR2, PFGFR, and EGFR, among others, represent acknowledged targets of semaphorins that are often associated with tumor progression or poor prognosis." (PMID 38067240, 2023). "It is evaluated using immunohistochemistry (IHC), and the expression of HER2 protein, encoded by ERBB2 gene, is scored on a scale of 0 to 3+ depending on staining intensity and the percentage of tumor cells positive for HER2." (PMID 38137385, 2023). "Recently, a CAR with two NKG2D structures and two ErbB2 scFv domains was designed to address the interference by soluble NKG2DLs and redirect NK cells to ErbB2‐positive tumor cells." (PMID 38045827, 2023). "Amplifications of EGFR and ERBB2 were found only in immune deficient MPNSTs (n = 3 tumours with ≥15 additional copies of EGFR and n = 1 tumour with 9 additional copies of ERBB2)." (PMID 37837931, 2023). "The immunohistochemical analysis of tumor tissue revealed variable expression of ERBB2 in HCC, and the location of the expressed cells was consistent with the results of immunofluorescence analysis." (PMID 37324014, 2023). "Multiple ErbB2-targeted therapeutics, such as trastuzumab (Herceptin), present clinical success in patients with multiple ErbB2 + tumor types." (PMID 36805678, 2023). "Together, the EGFR and ERBB2 (HER2) gene expression data show that CTCs can be a valuable source of tumor information." (PMID 36900406, 2023). "The role of TFAP2 in tumorigenesis involves the regulation of stemness and EMT, interactions between TFAP2 and the tumor microenvironment, the cell cycle and DNA damage repair, ER- and ERBB2-related signaling pathways, ferroptosis and the therapeutic response." (PMID 37291585, 2023). "Inhibition of ErbB2 on tumour cells or VEGF receptor 2 on ECs prevents the adhesion of breast tumour cells to the endothelium." (PMID 37830128, 2023). "Factors such as age, breast surgery type, concurrent DCIS, TNM stage, tumor grade, LVI, NI, HR status, and ERBB2 status were found to be associated with survival in patients with different histopathological types." (PMID 37624596, 2023). "Black patients with ERBB2+ disease were significantly more likely to have MAPK pathway alterations than White patients found with tumor next-generation sequencing." (PMID 36995716, 2023). "In a proof-of-concept analysis, we previously showed that the CAR-engineered cell line NK-92/5.28.z has strong in vitro cytotoxicity against ErbB2-positive tumor cell lines, including aRMS." (PMID 37662907, 2023). "In a cohort of 80 UM patients, ErbB2 (HER2) was expressed in all tumor samples and its expression was significantly higher than EGFR and ErbB4 (p<0.001)." (PMID 38021158, 2023). "Among the genomic biomarkers able to discriminate transformed tumours (hEMT, MES) from the epithelial state, we identified genes that have been previously linked with cell migration, invasion and EMT, such as RB1, VHL, ERBB2, ARHGAP26, PRDM1, APC." (PMID 36774358, 2023). "In another study using the HCC dataset, ERBB2 overexpression was identified by analyzing ERBB2 mRNA amplification, which was related to the tumor stage in HCC samples." (PMID 37174100, 2023). "ErbB2 is slightly increased in all tumor cell lines except for a significant increase in WM852 and undetectable in 1205Lu, similar to negligible if any levels in melanocytes." (PMID 36989239, 2023). "The most common genomic alterations leading to a recommendation were high tumor mutational burden TMBhigh (17.2%) and activating alterations in PIK3CA (13.8%) and ERBB2 (10.3%)." (PMID 37062035, 2023). "Recently, targeted therapies (e.g., antibodies against c-Kit, EGFR, VEGFR, ErbB2/HER-2) have been introduced when tumour-specific targets are available." (PMID 36975417, 2023).
tumor (continued). "The amplification of MYC, CCNE1, and ERBB2 was more frequently detected in CSF than in tumor tissue samples, with detection rates being 46.7% (7/15) vs 26.7% (4/15), 53.3% (8/15) vs 13.3% (2/15), and 26.7% (4/15) vs 13.3% (2/15), respectively." (PMID 37131253, 2023). "In mouse models of intestinal tumorigenesis, deletion of Erbb2 and Erbb3 has been reported to both increase and decrease the tumor burden, depending on the genetic background." (PMID 36912192, 2023). "In previous proof-of-concept analyses, we demonstrated the enhanced and CAR-specific cytotoxicity of NK-92/5.28.z cells compared to parental NK-92 cells against 2D ErbB2-positive RMS tumor cell lines." (PMID 37662907, 2023). "Aberrantly expressed MUC4 can act as a ligand for ERBB2, potentiate the phosphorylation of ERBB2, and reduce the binding of anti-ERBB2 antibodies to tumor cell surfaces." (PMID 37367035, 2023). "In addition, tumor heterogeneity may play a role as a cause for imprecise ERBB2 analysis." (PMID 37173881, 2023). "We then integrated Xenium and Visium data to derive differentially expressed genes from a tumor region containing cells expressing RNA of three receptors (ERBB2 + /ESR1 + /PGR+)." (PMID 38114474, 2023). "Whereas tumor stage was an independent prognostic factor for poor DFS in ERBB2-high cohort (< 0.001, Hazard ratio 1.295, 95% CI 1.154–1.458)." (PMID 37474724, 2023). "Of note, tumor cells were lysed to a high extent even at low E:T ratios of 5:1 and 2.5:1 and low ErbB2 surface expression of target cells by NK-92/5.28.z cells, but not by parental NK-92 cells." (PMID 37662907, 2023). "As a result, information on FGFR status, ERBB2 status, tumor molecular burden, etcetera, are missing." (PMID 37509315, 2023). "This approach destabilized and degraded ERBB2 and its kinases by overwriting the endogenous ERBB2 mRNA message across many cancer ERBB2 models and achieved primary tumor control in vivo." (PMID 37359373, 2023). "Herein, we report a case of a patient with metastatic HCC and a huge disease burden where a circulating tumor DNA (ctDNA) liquid biopsy done as part of our standard of care serendipitously revealed a very high ERBB2 copy number amplification (>78)." (PMID 40028484, 2023). "Our study explored the role of ERBB2/HER2 expression in UC with regards to the genomic landscape, tumor immune landscape, and clinical outcomes in a large database of real-world patient samples." (PMID 38136267, 2023). "In our study, higher serum ERBB2 levels were associated with an advanced BCLC stage, a larger tumor diameter, and the presence of PVTT." (PMID 37174100, 2023). "Trastuzumab binds an extracellular segment of the HER2 protein (Erbb2 in rodents), present on both tumour cells and cardiomyocytes." (PMID 37098605, 2023). "Our results showed that ERBB2 expression was significantly higher in HCC tumor tissues than normal tissues." (PMID 37324014, 2023). "The cytotoxic capacity of parental NK-92 and CAR-engineered NK-92.5.28.z cells was assessed against established, ErbB2-positive RH30GFP/luc+ tumor spheroids." (PMID 37662907, 2023). "Second, we categorized heterogeneous ERBB2-mutant tumor groups into three groups, each of which was found to have distinct biological characteristics." (PMID 37754252, 2023). "Given the possible interactions among ERBB2-low status, tumor stage, and receptor status, multivariable analysis was repeated separately by stage and receptor subtype." (PMID 36821125, 2023). "The 3′-idT modified ErbB2 aptamer showed higher tumor uptake and extended blood circulation time compared with unmodified aptamer in KPL4 xenografts." (PMID 37729138, 2023). "Trastuzumab, a monoclonal, anti-human ERBB2 protein antibody, inhibits tumor size and metastasis in vivo and in vitro through the upregulation of β-catenin and inhibition of SMAD3." (PMID 37174100, 2023).
tumor (continued). "ERBB2 demonstrated a moderate linear correlation with the maximal tumor diameter (Spearman’s ρ = 0.432, p = 0.001), and NRG4 demonstrated a moderate linear correlation with the number of tumors (Spearman’s ρ = 0.558, p < 0.001)." (PMID 37174100, 2023). "The endogenous CaMK-II inhibitor 1 (CAMK2N1) acts as a tumor suppressor, inhibiting ErbB2 downstream signaling pathways and hence cell proliferation and other cellular functions." (PMID 36979639, 2023). "High-expressing ERBB2 tumors have an increased expression of antibody drug conjugate (ADC) target genes NECTIN4 and TACSTD2 versus the low-expressing ERBB2 tumor." (PMID 38136267, 2023). "We highlight a small population of cells, a subcluster located in between tumor and myoepithelial populations which coexpress tumor (ERBB2, ABCC11) and myoepithelial markers (MYLK, DST) (a′)." (PMID 38114474, 2023). "Tumor cells that overexpress ErbB2 exhibit uncontrolled proliferation due to ligand-independent heterodimerization of ErbB2 and ErbB3 and the activation of downstream intracellular phosphoinositide-3-kinase (PIK3) and Akt signaling pathways." (PMID 38132657, 2023). "The CD19-4D5scFv engager enabled CD19 CAR T cells to recognize the ErbB2+ cancer cells and to suppress the ErbB2+ tumor growth." (PMID 36672182, 2023). "In the present study, the QCI® drug prediction algorithm recommended the highest number of drugs for ERBB2 amplified tumours, suggesting that this alteration is an attractive therapeutic target." (PMID 36670542, 2023). "In cell killing experiments, all tested TMs redirected NK cell cytotoxicity selectively to ErbB2-positive tumor cells." (PMID 36688995, 2023). "Similar to the correlation of expression and tumor grading, ERBB2 overexpression was detected in 39/61 advanced UTUCs staged 2–4, but only in 9 tumors staged 0 and in 13 tumors staged 1 (p > 0.359)." (PMID 37173881, 2023). "The intratumoral injection of 2×106 ErbB2-specific NK-92/5.28.z cells was performed once a week for 11 weeks, and significant inhibition of tumor growth was observed." (PMID 37251413, 2023). "STUB1, which is a co‐chaperone protein and U‐box‐containing E3 ligase, is involved in the degradation of several oncogenic proteins, including ErbB2, hypoxia inducible factor 1α, and c‐Myc, and consequently acts as a tumor suppressor." (PMID 35920319, 2023). "Next-generation sequencing on the tissue biopsy revealed a very high focal amplification of ERBB2, with 183 copies (unadjusted for tumor content)." (PMID 40028484, 2023). "Tyrosine kinase inhibitors—inhibition of EGFR and ERBB2/HER2 signaling pathways lead to tumor cell death, inhibition of cell growth, angiogenesis, and metastasis." (PMID 37039257, 2023). "For example, recurrent amplification of oncogenes such as MYC, ERBB2 (HER2), and FGFR1, and significant loss of tumor suppressors such as CDKN2A and CDKN2B were observed in the high-CRRS group." (PMID 36936912, 2023). "RNA-seq analyses further confirmed the correlation between risk of invasive progression and high expression of ERBB2 (HER2), PTK6 and Ki67, which have all been described previously as potential risk factors for tumor progression." (PMID 37116492, 2023). "Amplification of the ERBB2 gene on chromosome 17, which encodes the human epidermal growth factor receptor 2 protein (HER2), is a well-characterized targetable finding in tumors of the upper gastrointestinal tract, breast, and endometrium." (PMID 37449085, 2023). "In conclusion, this work demonstrates that PPRHs are effective for inhibiting ERBB2 gene expression both in vitro and in vivo, and this strategy can reduce cancer cell viability and tumor growth." (PMID 37108234, 2023). "Dacomitinib (EGFR, ErbB-2, and ErbB4, irreversible inhibitor) was efficient in inhibiting the tumor volume of HNSCC and acted as a radiosensitizing agent in HNSCC." (PMID 36646686, 2023).